ACLY (ATP citrate lyase)
Diseases named in the same sentence as ACLY in open-access papers (continued):
Sharing a sentence is not in itself a finding about the gene and the disease.
cancer (continued). "In this study, we show that SIRT6 deficiency increases the nuclear ACLY protein, nuclear acetyl-CoA abundance, and locus-specific histone acetylation, which in turn drive an up-regulation of PDGFRA and other genes that contribute to invasive cancer cell adhesion and migration phenotypes." (PMID 34573442, 2021). "Likewise, inhibition of ATP-citrate lyase, the enzyme responsible for the conversion of cytosolic citrate to acetyl-CoA results in the downregulation of the transcriptional factor Snail, a key regulator of stemness phenotype in cancer stem cells." (PMID 34249759, 2021). "ACLY occupies a privileged position at the crossroads of the metabolism of cancer cells by linking both the glycolysis and lipid metabolism, having been found overexpressed in many aggressive cancers, and might play an important role in cancer relapse." (PMID 34823530, 2021). "The AKT-mediated phosphorylation of ACLY could promote histone acetylation in cancer cells and immune cells to response to the oncogenic and cytokine-induced signaling, while ACLY is transcriptionally regulated by SREBP1 (sterol regulatory element binding transcription protein-1)." (PMID 33194756, 2020). "Therefore, the researchers proposed that ACLY may play an important role in the USP13-mediated deubiquitination to promote cancer development." (PMID 33194756, 2020). "The truncated TCA cycle in cancer cells, due to aconitase knockdown, results in citrate accumulation and efflux into cytosol, where it is converted into acetyl-CoA and oxalacetate by ATP citrate lyase (ACLY), allowing lipid synthesis from acetyl-CoA, and gluconeogenesis." (PMID 32679735, 2020). "Silencing ACLY was also shown to decrease histone acetylation in several mammalian cell types, indicating that mitochondrial-derived citrate plays a role in tumorigenesis by indirect alterations in transcriptional programs that dictate cancer cell formation and progression." (PMID 30809153, 2019). "Thus, normal cells useglycolysis to produce pyruvate that is transferred to the mitochondria to produceacetyl-CoA for further utilization in the tricarboxylic acid cycle, but cancer cells produce citrate thatis converted in the cytoplasm into acetyl-CoA by the ATP citrate-lyase (ACL)." (PMID 29026007, 2017). "Therefore, inhibition of ACLY and blockade of lipid accumulation may be favorable in other aggressive cancer types with high LMW-E expression such as ovarian, colorectal cancers and melanoma." (PMID 28399876, 2017). "Moreover, silencing of ACLY has been shown to block cancer cell growth both in vivo and in vitro." (PMID 24203995, 2013). "In the nucleus, ATP citrate lyase (ACLY) provides acetyl-CoA for histone acetylation at double-strand breaks, increasing radioresistance in cancer cells." (PMID 41596341, 2026). "In cancer cells, SLC25A1 drives the translocation of citrate from the mitochondria to the cytoplasm and provides substrate for ATP citrate lyase (ACLY) to generate acetyl-CoA." (PMID 41513612, 2026). "Cancer‐related genes, such as AKT, influence acetyl‐CoA levels in cancer cells by enhancing the phosphorylation of ACLY, thereby sustaining acetyl‐CoA production and promoting histone acetylation." (PMID 40060193, 2025). "FASN, ACACA, ACLY, and ACSL4 are considered key enzymes in lipid metabolism, and previous studies have shown that they can promote the proliferation of various cancers." (PMID 39891099, 2025). "MiR-22 modulates key metabolic genes including ATP citrate lyase (ACLY) and enolase 1 (ENO1) in different cancer types, suggesting its prominent role in modulating the so-called “Warburg effect”." (PMID 40332478, 2025). "After the knockdown of ACLY and SREBPs, CRC cell proliferation, metastasis, and lipid production were inhibited, while apoptosis of cancer cells was enhanced." (PMID 40060193, 2025).
cancer (continued). "Further studies have proven that, in cancer cells, the PI3K/AKT signaling pathway promotes the expression of ATP citrate lyase (ACL), ACC, and FASN by upregulating SREBP-1." (PMID 40432434, 2025). "Functionally, ACLY contributes to HCC progression by activating the Wnt/β-catenin signaling pathway, thereby promoting cancer stemness and metastasis." (PMID 41154605, 2025). "Many key enzymes of lipid synthesis and metabolic processes, such as ACLY, FASN, and SCD1, are highly expressed in cancers, promoting cell proliferation while enhancing cell stemness." (PMID 40002387, 2025). "Consistent with this assumption, cancer cells often show upregulation of genes involved in fatty acid synthesis, such as SREBP-1, ACC1, fatty acid synthase (FASN), and ATP citrate lyase (ACLY)." (PMID 40563460, 2025). "While direct evidence of ACLY’s role in PCa is limited, its involvement in feedback loops with ACLY/AMPK/AR in other cancers suggests potential implications for tumor growth and therapy resistance in PCa." (PMID 41009695, 2025). "Several enzymes involved in de novo fatty acid synthesis, including FASN, ACLY, SCD, and ACSS2, are abnormally expressed in various cancers, promoting fatty acid synthesis and contributing to malignant tumor phenotypes." (PMID 41285764, 2025). "Enzymes such as ACLY, ACSS2, and ACC1 are widely upregulated in various cancers, including CRC, underscoring their critical roles in the metabolic hub centered on acetyl‐CoA." (PMID 40060193, 2025). "Critical enzymes in the lipid metabolism pathway, such as acetyl coenzyme A carboxylase 1 (ACC1), fatty acid synthase (FASN), ATP citrate lyase (ACLY), and carnitine palmitoyltransferase 1 (CPT1A), are upregulated across a broad spectrum of cancers." (PMID 41145471, 2025). "Targeting FA synthesis by inhibiting FASN, ACLY, and ACSS2 has been the subject of numerous preclinical and several clinical studies in various cancers, including breast, lung, colon, prostate, and bladder." (PMID 40723225, 2025). "Inhibitor of growth 5 (ING5) upregulated the expression of acetyl-CoA carboxylase 1 (ACC1) and ATP-citrate lyase (ACLY) and mediated tumor lipogenesis, which is involved in the malignant progression of cancers." (PMID 40867514, 2025). "These cancer cells develop de novo FA synthesis with increased activity of multiple lipogenic enzymes, ACC, ACLY, CoA carboxylase (ACACA), and SCD." (PMID 39332525, 2024). "Higher levels of certain enzymes, such as ATP-citrate lyase (ACLY), ACSS1, and ACSS2, have been observed in certain cancer types, promoting tumor growth and metastasis by providing an alternative energy source to glucose." (PMID 39456967, 2024). "Conversely, high ACLY expression was negatively correlated with the G2M checkpoint, MYC targets, and E2F targets, indicating an inverse relationship with cancer proliferation and anti-tumor immunity." (PMID 39399493, 2024). "Human ATP citrate lyase (ACLY) and fatty acid synthase (FASN) are fundamental multi‐enzymatic activity proteins for citrate to be metabolized in cancer cells." (PMID 38425123, 2024). "ATP citrate lyase (ACLY), acetyl-CoA carboxylase (ACC), and fatty acid synthase (FASN) are the most highly expressed lipogenic enzymes in several forms of cancer." (PMID 38933330, 2024). "Accordingly, ACLY (ATP citrate lyase) and FASN (fatty acid synthetase) which are involved in de novo fatty acid synthesis are both greatly upregulated in cancer cells." (PMID 38402237, 2024). "Thus, ACLY splicing may be component of an ESRP1-dependent program that relates cancer phenotypes." (PMID 38815867, 2024). "ACLY is a substrate of AKT, and signaling between AKT and ACLY promotes the production of acetyl-CoA and global increases in histone acetylation in cancer cells." (PMID 38535331, 2024). "Specifically, targeting key enzymes involved in fatty acid synthesis (SREBP, ACLY, ACC, FASN, and SCD) has been identified as a potential strategy for cancer therapy." (PMID 38189049, 2023).
cancer (continued). "In a variety of cancer types, a considerable number of drugs that can inhibit the synthesis of SREBP, ACLY, ACC, FASN, SCD, and PPARα have been tested for anticancer effects in preclinical and clinical studies." (PMID 38189049, 2023). "ACLY, FASN, SCD, and ACC are considered key enzymes for fatty acid synthesis and have been reported to promote proliferation in several types of cancers." (PMID 37821935, 2023). "In this study, after the pharmacological combined inhibition of PLK1 and ACLY, the mRNA expression levels of SREBF1 and MYC were significantly decreased in most pan-cancer cell lines." (PMID 37958642, 2023). "This pathway is controlled by lipogenic metabolic enzymes, including ATP-citrate lyase (ACLY), acetyl-CoA carboxylase (ACC) and fatty acid synthase (FASN), which are upregulated in some cancer cells." (PMID 37444561, 2023). "Coherently, in A549 cells, ACLY knockdown (increasing citrate level) inhibits PI3K/AKT and reverses cancer stemness and EMT, especially by reducing Snail expression." (PMID 35626081, 2022). "A direct relationship has been established in the activity and expression of ACLY and CPT1 in cancer cells." (PMID 35178152, 2022). "Compared with the ACLY inhibitors, the researches of ACC inhibitors and ACSS2 inhibitor in cancers need to be increased." (PMID 39086974, 2022). "Inhibition of key enzymes for FAs synthesis, such as FASN (presented above), ATP-citrate lyase (ACLY) and ACC can decrease the proliferation and growth of different cancer cells." (PMID 35433453, 2022). "The enzymes of lipogenesis are increased in various cancers, including HCC, such as ATP citrate lyase (ACLY), acetyl-CoA carboxylase (ACC), fatty acid synthase (FASN), acyl-CoA synthease (ACS) and stearoyl-CoA-desaturase 1 (SCD1)." (PMID 36612019, 2022). "Among them, we observed overexpression of ACLY significantly increased the levels of intracellular free fatty acid and triglyceride, and activated AKT/mTOR pathway to promote cancer development." (PMID 36064336, 2022). "Indeed, ACLY inhibitors could be a potential therapeutic alternative in cancer." (PMID 36578540, 2022). "In summary, we identified a previously undescribed signaling pathway of the USP22-PPARγ-ACLY/ACC axis that plays an important role in lipogenesis and HCC tumorigenesis and provides an option for cancer therapy targeting fatty acid synthesis." (PMID 35449157, 2022). "Key enzymes for lipid metabolism such as ATP citrate lyase (ACLY), fatty acid synthase (FASN), and stearoyl-CoA desaturase 1 (SCD1) can be differentially expressed in NSCLC compared to non-cancer tissue." (PMID 34822397, 2021). "In this study, we targeted two enzymes known to be altered in cancer cells: pyruvate dehydrogenase (PDH), which is downregulated, and ATP citrate lyase (ACL), which is overexpressed." (PMID 34073567, 2021). "In consideration of ACLY and IGF1R as promising therapeutic targets, we further designed a pharmacological strategy to verify their crucial anti-cancer roles." (PMID 34075028, 2021). "FASN uses substrates produced by the consequent activities of ACACA and ACLY enzymes, which, together with FASN have also been found to be deregulated in a number of cancer types." (PMID 34206240, 2021). "ATP citrate lyase (ACLY) is another key enzyme responsible for generating cytosolic acetyl-CoA and oxaloacetate which are important metabolites for cancer cells." (PMID 33916219, 2021). "The most important enzymes in lipid metabolism, such as Acetyl-CoA Carboxylase (ACC), Fatty Acid Synthase (FASN), ATP Citrate Lyase (ACLY), Phospholipase D1 (PLD1), Stearoyl-CoA Desaturases 1 (SCD1), are closely related to cancer metastasis." (PMID 33718168, 2021).
cancer (continued). "Accordingly, ACLY knockdown reverses EMT and cancer stemness, especially by reducing Snail expression." (PMID 34205414, 2021). "Rate‐limiting enzymes for FAs synthesis, such as FASN, ACLY, and ACC, are significantly upregulated in cancer cells, and inhibition of these enzymes can decrease the proliferation and growth of cancer cells." (PMID 34766135, 2021). "In cancer cells, to prevent the suppression of glycolysis, citrate is rapidly converted into OAA and acetyl-CoA by ACLY, which is overexpressed." (PMID 33282912, 2020). "Among lipogenic enzymes, ATP citrate lyase (ACLY), the rate-limiting enzymes acetyl-CoA carboxylase (ACC) and fatty acid synthase (FAS), are the most expressed enzymes in many cancer types." (PMID 33339398, 2020). "Among SREBP1-regulated FA synthesis genes, ACLY, ACC, FASN, and SCD1 have been reported to be highly expressed in cancers." (PMID 33233362, 2020). "Under metabolic stress such as hypoxia or lipid depletion, cancer cells upregulate acetyl-CoA synthetase 2 (ACSS2) to generate acetyl-CoA from acetate, or increase ATP-citrate lyase (ACLY) to convert citrate into acetyl-CoA." (PMID 33233362, 2020). "In fact, ATP-citrate lyase (ACLY), the enzyme that splits mitochondria-originated citrate into acetylCoA and α-ketoglutarate, was long recognized for its role in cancer and as a therapeutic target." (PMID 33233365, 2020). "Overall, key players in FA synthesis, such as ATP-citrate lyase (ACLY), acetyl-CoA carboxylase (ACC) and fatty acid synthase (FASN), are elevated in cancer cells." (PMID 32641978, 2020). "Further study is needed to investigate ACLY, SLC2A1, and KAT2A in the histone acetylation function across cancer types." (PMID 31828117, 2019). "We analyzed the expression of five major DNFA enzymes SCD, FASN, ACLY, ACSS2 and ACACA using RNA-Seq data from 30 diverse cancer types in The Cancer Genome Atlas (TCGA)." (PMID 31316083, 2019). "ACLY, SLC2A1, KAT2A, and DNMT3B are the critical genes contributing to epigenetic dysfunction across cancers." (PMID 31828117, 2019). "The genes ACLY, CS, RPE, and IDH2 were found to be among the top 10% of the genes that were frequently overexpressed across 19 cancer types from a meta-analysis study of 1981 tumors (FDR p value < 0.05)." (PMID 30823893, 2019). "Our research clarifies some key metabolic genes, ACLY, SLC2A1, KAT2A, and DNMT3B, which are most disordered and indirectly contribute to the dysfunction of histone acetylation and DNA methylation in cancer." (PMID 31828117, 2019). "For example, ACLY, ACSS2, and PDC have been considered as potential molecular targets for anti-cancer therapy due to their functions in nuclear acetyl-CoA production and histone acetylation." (PMID 30283496, 2018). "Met downregulated expression of enzymes of fatty acid de novo synthesis, such as ATP Citrate Lyase (ACLY), Fatty Acid Synthase (FAS), Fatty Acyl-CoA Elongase 6 (ELOVL6), and Stearoyl-CoA Desaturase-1 (SCD1) in cancer cells." (PMID 28230778, 2017). "Lipogenic enzymes, such as FASN, ACC, and ACLY that are required for fatty acid biosynthesis, and SREBP1, the master regulator of lipogenic gene expression, are overexpressed in many cancers, including breast." (PMID 28421159, 2017). "USP13 upregulates ACLY and OGDH, two key regulators that drive glutaminolysis, ATP generation and lipid synthesis in cancer metabolism." (PMID 27892457, 2016). "To further clarify the effects of OGDH and ACLY on de novo fatty acids synthesis in OVCA, we used [U-13C5] glutamine or [U-13C6] glucose to culture cancer cells for 72 h." (PMID 27892457, 2016). "The enzymes ATP-citrate lyase (ACL), acetyl-CoA carboxylase (ACC), and the fatty acid synthase (FAS) are frequently overexpressed in cancer cells." (PMID 23762063, 2013).
cancer (continued). "ATP citrate lyase (ACL), a key enzyme in de novo lipid synthesis, has been reported to be overexpressed or activated in several cancer types." (PMID 22266777, 2012). "High activity levels of ATP-citrate lyase, ACC and FAS, which respectively catalyzes the sequential synthesis of acetylCoA, malonylCoA and palmitic acid, have been shown to be essential for cancer cell proliferation." (PMID 19710915, 2009). "We observed a significant upregulation of ACLY, FASN, and SCD1 in primary cancer and CRPC samples." (PMID 39988626, 2025). "Acetyl-CoA, produced via pyruvate dehydrogenase (PDH) or ATP citrate lyase (ACLY), serves as a critical cofactor for histone acetyltransferases (HATs), linking glucose metabolism to epigenetic regulation and gene transcription in cancer cells." (PMID 40734168, 2025). "Inhibition of ACLY leads to PUFA peroxidation and mitochondrial damage, thereby triggering mitochondrial DNA leakage to activate cGAS-STING innate immune pathway, which up-regulates the expression of PD-L1 immune checkpoint in cancer cells." (PMID 41421797, 2025). "sEVs also modulate lipid metabolism in cancer by upregulating X-inactive specific transcript (XIST), which suppresses miR-655 and activates downstream signaling pathways that increase ATP citrate lyase (ACLY) expression." (PMID 41322698, 2025). "Targeting the lipid and cholesterol dependence of cancer cell inhibitor agents directed against lipogenic enzymes (FASN, ACLY and ACC) has been the subject of numerous studies; and their efficacy as anticancer therapies has been proven in various preclinical models of carcinogenesis." (PMID 38263248, 2024). "Besides its role in regulating cancer development through the PI3K-AKT pathway, ACLY is often excessively expressed in different human cancers." (PMID 38933330, 2024). "As ACLY and ACSS2 have also been found to provide substrates for histone acetylation, modulation of acetyl-CoA metabolism can also affect gene expression programmes in cancer cells." (PMID 39251875, 2024). "Inhibition of ACYL in CSCs has not shown significant effects due to the compensatory role of ACSS2, which replenishes acetyl-CoA in the absence of ACLY in cancer models." (PMID 39456967, 2024). "To investigate this, we generated cancer cell lines lacking both ACLY and ACSS2 [double knockout (DKO) cells]." (PMID 37134161, 2023). "Intriguingly, we show that in contrast to fibroblasts, cancer cells lacking both ACLY and ACSS2 [double knockout (DKO) cells] are viable, proliferate, contain a nuclear-cytosolic pool of acetyl-CoA, and sustain protein acetylation." (PMID 37134161, 2023). "The targeting of ACLY and PLK1, or alternatively, the simultaneous targeting of other dysregulated metabolic pathways while starting from cell-cycle-related proteins, presents novel prospects for cancer treatment." (PMID 37958642, 2023). "Metabolites can regulate chromatin or protein acetylation (e.g., c-MYC, HIF-1α, GAPDH, PKM2, PEPCK, 6PGD, ACLY, LCAD, and BCAT2), histone succinylation, butyrylation, lactylation, phosphorylation, citrullination, and itaconation, and further contribute to cancer progression." (PMID 36831413, 2023). "In cancer cell lines lacking both ACLY and ACSS2, we show that a pool of cytosolic acetyl-CoA is maintained, that histone acetylation is active, and that both glucose and fatty acids can supply acetyl-CoA." (PMID 37134161, 2023). "In addition, a significant reduction in CDK2 mRNA expression was observed across all tested pan-cancer cell lines upon the pharmacological co-inhibition of PLK1 and ACLY." (PMID 37958642, 2023). "In general, the ACLY inhibitors are still in the preclinical research, but there is no denying that their great effects in inhibiting cancer." (PMID 39086974, 2022). "Several key enzymes involved in the de novo synthesis pathway, such as ACLY, ACC, and FASN, are significantly up-regulated, suggesting that these enzymes may be potential drug targets for inhibiting cancer progression." (PMID 36588702, 2022).